MIR128-1 (microRNA 128-1)
Synonyms: hsa-mir-128a; hsa-mir-128-1; mir-128-1; MIR128A; MIRN128-1; MIRN128A
Gene: MicroRNA gene on chromosome 2 (135,665,397 to 135,665,478, forward strand). Ensembl gene ENSG00000207654.
Gene Ontology:
Cellular component: RISC complex
Homologues: Orthologues: rabbit MIR128-1 (100% identical), rat Mir128-1 (100% identical), dog MIR128-1 (98% identical), pig MIR128-1 (95% identical), guinea pig MIR128-1 (85% identical), mouse Mir128-1 (85% identical), tropical clawed frog xtr-mir-128-1 (83% identical), chimpanzee MIR128-1 (79% identical), macaque MIR128-1 (79% identical), zebrafish mir128-2 (70% identical). Paralogues in human: MIR128-2 (71% identical).
Diseases named in the same sentence as MIR128-1 in open-access papers:
MIR128-1 is named in the same sentence as 1 disease in open-access papers, as found by Europe PMC text mining. Sharing a sentence is not in itself a finding about the gene and the disease. The quoted sentences say what the papers report.
cancer (2 papers, 2021 to 2023). A tumor composed of atypical neoplastic, often pleomorphic cells that invade other tissues. "Subsequently, MIR128-1 is considered a key biomarker for the diagnosis and prognosis of cancers, as well as an effective agent for targeted therapy of malignant tumors." (PMID 33920789, 2021). "Furthermore, MIR128-1 targets several oncogenes governing tumor proliferation, differentiation, apoptosis, invasion, and metastasis, providing essential cues for the development of novel therapeutic strategies for cancer prevention and treatment." (PMID 33920789, 2021). "Among the 850 hypoxia-related genes, 6 genes (LOC101928143, LOC102723407, MIR1281, PLA2G4B, SLC5A10, and G6PC1) were absent from the TCGA pan-cancer RNA-seq data; thus, 844 genes with RNA expression values were used in the analysis." (PMID 38248716, 2023).